HSD3B1 (hydroxy-delta-5-steroid dehydrogenase, 3 beta- and steroid delta-isomerase 1)
Diseases named in the same sentence as HSD3B1 in open-access papers (continued):
Sharing a sentence is not in itself a finding about the gene and the disease.
prostate carcinoma (continued). "HSD3B1 encodes the rate-limiting enzyme for nongonadal androgen synthesis, 3β-hydroxysteroid dehydrogenase-1, and has a common adrenal-permissive missense-encoding variant that confers increased synthesis of potent androgens from nongonadal precursor steroids and poorer prostate cancer outcomes." (PMID 39286977, 2024). "While studies of HSD3B1 have yielded intriguing insights, the host of other APUC genes and their genetic or somatic perturbations have also been examined in prostate cancer and beyond." (PMID 37435458, 2022). "Furthermore, another source of androgen in prostate cancer is the de novo androgen synthesis in prostate cancer cells, mediated by CYPA1 and 3β-dehydroxysteroid dehydrogenase isoenzyme 1 (3βHSD1 or HSD3B1)." (PMID 34710984, 2021).
breast carcinoma (11 papers, 2016 to 2025). "A potential application of these data is incorporation of HSD3B1 genotype status into breast cancer risk models." (PMID 34520399, 2021). "Such patients are frequently worried about the risk of developing a second breast cancer, and knowing the HSD3B1 genotype information may add to an individualized risk/benefit discussion, especially when concerns about endocrine therapy adherence arise." (PMID 34520399, 2021). "Assessment of this variant independently may be important for clinicians given the hypothesized impact of this variant specifically for postmenopausal breast cancer due to the role of HSD3B1 in adrenally mediated estrogen biosynthesis." (PMID 34520399, 2021). "We hypothesized that homozygous inheritance of the adrenal-permissive HSD3B1(1245C) is associated with postmenopausal estrogen receptor–positive (ER-positive) breast cancer." (PMID 34520399, 2021). "Here, we tested the hypothesis that the more rapid metabolism associated with the adrenal-permissive HSD3B1(1245C) allele is associated with estrogen-driven breast cancer in postmenopausal women." (PMID 34520399, 2021). "Using ER+ breast cancer models with distinct HSD3B1 genotypes, we demonstrate that therapy-resistant cells upregulate 3βHSD1 activity to sustain survival and ER signaling." (PMID 40544998, 2025). "This further confirms that LRH1 facilitates DHEA metabolism to estrogens and supports breast cancer cell survival under endocrine therapy pressure by upregulating HSD3B1 expression." (PMID 40544998, 2025). "We establish HSD3B1 as a critical mediator of endocrine resistance in ER+ breast cancer, with genotype-dependent regulation and LRH1-driven transcriptional control." (PMID 40544998, 2025). "The mechanism of HSD3B1 in the development of AI resistance in HR-positive breast cancer has been documented earlier." (PMID 37415453, 2023). "The frequency of the homozygous adrenal-permissive HSD3B1 genotype is enriched in women with estrogen-driven postmenopausal breast cancer and occurs in about 15% of these tumors." (PMID 36647826, 2023). "KDM5B, ARSB, AKR1C3, HSD3B1, ESRRB are involved in steroid hormone metabolism and have been found to be associated with other hormone-dependent tumors, such as prostate and breast cancers." (PMID 36742386, 2023). "The homozygous adrenal-permissive HSD3B1 genotype is enriched in ER-positive postmenopausal breast cancer." (PMID 37009898, 2023). "When they conducted genetic knockdown of HSD3B1 or applied pharmacologic inhibition of 3βHSD1 with trilostane, they observed attenuation of cellular proliferation and migration of breast cancer cell lines." (PMID 37435458, 2022). "A prospective study of postmenopausal ER-driven breast cancer was done for determination of HSD3B1 and circulating steroids." (PMID 34520399, 2021). "Our work mechanistically links HSD3B1 induction to LRH1 in breast cancer steroidogenesis." (PMID 40544998, 2025). "Targeting HSD3B1 or LRH1 may offer a new therapeutic strategy to restore endocrine sensitivity in ER+ breast cancer." (PMID 40544998, 2025). "However, its role in primary tumors of 258 breast cancer patients showed that around 44% of patients were HSD3B1 positive and knockdown of HSD3B1 inhibited both cell proliferation and cell migration irrespective of estrogen receptor action." (PMID 39342193, 2024). "This genetic evidence for HSD3B1 in driving breast cancer therefore suggests that the fibroblast-glucosamine-3βHSD1 axis may also play an essential role in breast cancer pathogenesis." (PMID 37009898, 2023). "HSD3B1 and its genetic variations play a role in breast cancer." (PMID 37435458, 2022). "In our previous report, we suggest that increased expression of HSD3B1 might reduce sensitivity to aromatase inhibitors (AIs) in human breast cancer cell lines, as demonstrated by enhanced 3β‐diol‐induced ER activation and growth mechanisms." (PMID 27139182, 2016).
breast carcinoma (continued). "We show that long-term estrogen deprivation (LTED) or tamoxifen treatment induces HSD3B1 expression and enzymatic activity, sustaining DHEA metabolism and ER signaling in resistant ER+ breast cancer cells." (PMID 40544998, 2025). "We found a positive correlation between HSD3B1 and NR5A2 expression in hormone therapy-treated breast cancer patients." (PMID 40544998, 2025). "Our findings showed that LRH1 inhibition significantly decreases HSD3B1 expression, while LRH1 overexpression increases it, supporting a conserved regulatory mechanism across multiple breast cancer models." (PMID 40544998, 2025). "However, the regulation of HSD3B1 in endocrine-resistant breast cancer remains unclear." (PMID 40544998, 2025). "Collectively, our findings suggest that HSD3B1 is upregulated in LTED and tamoxifen-treated breast cancer cells, enhancing DHEA metabolism, sustaining ER signaling, and promoting cell survival." (PMID 40544998, 2025). "We found that the HSD3B1 gene was upregulated in the resistant samples, indicating the increased expression of HSD3B1 in breast cancer patients on treatment with the non-steroidal AI drugs (anastrozole and letrozole)." (PMID 37415453, 2023). "The HSD3B1(1245A/C) SNP (rs1047303) has not previously been identified in GWAS for breast cancer." (PMID 34520399, 2021). "Further in vitro and in vivo studies are required to support the involvement of CDC20B, HSD3B1, and CDKN2A, as possible prognostic biomarkers of non-steroidal AI resistance in breast cancer." (PMID 37415453, 2023).
metastatic disease (7 papers, 2021 to 2025). "We confirmed that the gain-of-function allele in HSD3B1 rs1047303 is associated with greater PC mortality in men with metastatic disease." (PMID 33921650, 2021). "We hypothesized that up-front pharmacologic blockade by use of AR antagonists alone with ADT would reverse the poor outcomes and survival associated with the adrenal-permissive HSD3B1 allele in patients with LV metastatic disease." (PMID 39286977, 2024). "Our findings suggest the HSD3B1 CC genotype is associated with inferior PCSM among all patients and in individuals who develop metastatic disease." (PMID 38506808, 2024). "All clinical associations to this point have focused on the link between the adrenally permissive HSD3B1 and prognosis in advanced, metastatic disease." (PMID 37966114, 2023). "Of the many APUC genes that have been associated with the activation of AR, we found that 6 (HSD3B1, HSD3B2, CYP11A1, CYP11B1, CYP17A1, and CYP3A43) exhibit robust association in prostate and metastatic tumors and were mutually exclusive with heightened AR activity." (PMID 39207857, 2024). "HSD3B1 rs1047303 and YBX1 rs12030724 significantly impacted patients’ OS among those with non-metastatic disease at diagnosis and under AbA-based treatment for mCRPC." (PMID 39337362, 2024). "Six APUC genes (HSD3B1, HSD3B2, CYP3A43, CYP11A1, CYP11B1, CYP17A1) exhibited coalescent gene behavior in a cohort of metastatic tumors (n = 208)." (PMID 39207857, 2024).
hypospadias (6 papers, 2020 to 2025). Hypospadias is the displacement of the urethral meatus on the ventrum of the penis. "Carmichael and colleagues detected one SNP in HSD3B1 which was associated with moderate hypospadias through sex hormone biosynthesis and metabolism (Carmichael, Witte, Ma, Lammer, & Shaw, 2014)." (PMID 32515122, 2020). "Additionally, its human homologs, HSD3B1 and HSD3B2, are associated with hypertension and hypospadias, further highlighting the importance of Hsd3b3 and its human counterparts in steroid hormone biosynthesis." (PMID 41293248, 2025). "Compound rare damaging mutants of AR gene with HSD3B1 and SLC25A5 genes were identified in the different severe hypospadias." (PMID 32515122, 2020). "Polymorphisms, mutations, and epigenetic changes in the AR, CYR61, HSD17B3, HSD3B1, MAMLD1, SRD5A2, and STARD3 have been associated to hypospadias risk in severe types of hypospadias that have not been found in mild hypospadias." (PMID 33425810, 2020).
Hypertension (5 papers, 2011 to 2025). The presence of chronic increased pressure in the systemic arterial system. "The data obtained applying Likelihood-ratio tests and Wald statistical tests indicate that HSD3B1 polymorphism subgroups' status was significantly associated with hypertension in patients who died." (PMID 35874037, 2021). "When we looked at probability of death, we observed a similar association between the C allele of HSD3B1 and hypertension." (PMID 35874037, 2021). "The HSD3B1 is related to Hypertensive disease and other diseases." (PMID 36210804, 2022). "In addition, also in this case, we can see that the higher risk of death, that hypertension confers to patients infected with SARS-CoV-2, seems to be driven by HSD3B1 genetic status." (PMID 35874037, 2021). "However, the relationship is unclear and disputed in a small-scale clinical study indicating that genetic variation in HSD3B1 affects blood pressure and hypertension in APA patients." (PMID 27057163, 2016). "The relationship between AR pathway and diabetes or hypertension deserves further investigation because, to the best of our knowledge, the role played by HSD3B1 with these comorbidities has never been investigated." (PMID 35874037, 2021).
preeclampsia (5 papers, 2013 to 2024). Preeclampsia is a hypertensive disorder of pregnancy that is characterized by new-onset hypertension with proteinuria presenting after 20 weeks of gestation, and depending on mild or severe forms may initially present with severe headache, visual disturbances, and hyperreflexia. "In the conversion of DHEA to androstenedione by HSD3B1, both metabolites were elevated in preeclampsia." (PMID 39684415, 2024). "Hogg, K demonstrated significant hypomethylation of HSD3B1 in the placenta of early-onset preeclampsia." (PMID 36263435, 2022). "Significant DNA hypomethylation was observed in preeclampsia for steroidogenic genes, including CYP11A1 for cytochrome P450scc and HSD3B1 for 3β-hydroxy-delta-5-steroid dehydrogenase type 1, each controlling the two-step pathway of progesterone synthesis from cholesterol." (PMID 26068234, 2015). "Maternal progesterone, but not estrogen, concentrations are increased in women with preeclampsia and both steroid hormones positively stimulate CYP11A1 and HSD3B1 expression in trophoblast cells." (PMID 23667551, 2013).
endometrial cancer (4 papers, 2017 to 2025). Primary or metastatic malignant neoplasm involving the endometrium (mucous membrane that lines the endometrial cavity). "Based on this study and our study on endometrial cancer, we recommend follow-up of interactions between acrylamide intake and SNPs for ovarian and endometrial cancer risk, particularly SNPs in CYP2E1, GSTs, the HSD3B1/B2 gene cluster, AKR1C1, NQO1, GPX1 and MGC12965." (PMID 28391539, 2017). "As the HSD3B1 genotypes contribute to differences in local and adrenal steroid production, their transcriptional and phenotypic effects on cancers influenced by hormonal signaling such as BC and endometrial cancer (EC)—particularly in relation to menopausal status—remain unclear." (PMID 40565184, 2025).
ovarian carcinoma (3 papers, 2017 to 2019). A malignant neoplasm originating from the surface ovarian epithelium. "This study showed nominally statistically significant interactions between several SNPs in the HSD3B1/B2 gene cluster and acrylamide intake for ovarian cancer risk, suggesting that acrylamide may cause ovarian cancer through effects on sex hormones." (PMID 28391539, 2017).
prostate tumor (3 papers, 2021 to 2025). "Our novel findings indicated that the adrenal-permissive state of HSD3B1 is associated with differences in the immune microenvironment of prostate tumors, but in a tissue-site-specific manner." (PMID 40282446, 2025). "Our study indicates that in prostate tumors, HSD3B1 germline status is associated with novel functions beyond androgen signaling." (PMID 40282446, 2025). "Using samples from the Caris database, we interrogated the association between HSD3B1 germline variants and somatic features in diseased prostate tumor tissue." (PMID 40282446, 2025). "This differential expression of genes expressed on the prostate tumor cell surface, or genes that are immune therapy targets, indicates a need to evaluate HSD3B1 genotypes when considering these therapies." (PMID 40282446, 2025).
androgen excess (2 papers, 2018 to 2025). "In Lrp2high TC, Cyp17a1 and Hsd3b1 are predominantly expressed, with Cyp17a1 showing particularly high levels, emphasizing this subpopulation’s role in androgen excess in PCOS." (PMID 40831751, 2025).
COVID-19 (2 papers, 2021 to 2024). A disease caused by infection with severe acute respiratory syndrome coronavirus 2. "Our aim was to characterize the HSD3B1 polymorphism status and its potential association with clinical outcomes in hospitalized patients with COVID-19 in Southern Switzerland." (PMID 35874037, 2021). "Based on a possible influence of the AR pathway on SARS-CoV-2 infection severity, our aim was to explore the potential association between the HSD3B1 gene polymorphism and clinical outcome in a series of patients who underwent hospitalization due to COVID-19 in Canton Ticino (Switzerland)." (PMID 35874037, 2021).
Follicular Cyst (2 papers, 2023). Cyst due to the occlusion of the duct of a follicle or small gland. "Some researchers reported that follicular cysts appear to be associated with changes in the transcription of IRs, IGFRs, PAPP-A and HSD3B1 and LH receptor genes, as well as a decreased expression level of estrogen receptor β protein and a promoted expression level of estrogen receptor α protein." (PMID 37958056, 2023).
gastric cancer (2 papers, 2012 to 2017). A primary or metastatic malignant neoplasm involving the stomach. "The objective of the study was to investigate the role of genes (HSD3B1, CYP17A1, CYP19A1, HSD17B2, HSD17B1) involved in the steroid hormone biosynthesis pathway and progesterone receptor (PGR) in the etiology of gastric cancer in a population-based two-phase genetic association study." (PMID 23110082, 2012).
melanoma (2 papers, 2019 to 2020). A malignant, usually aggressive tumor composed of atypical, neoplastic melanocytes. "Amplification of the HSD3B1 gene was highest (~5%) in melanoma and none in colorectal cancer." (PMID 31060224, 2019). "Human melanoma tissues represented a prominent steroidogenic tumor type, expressing CYP11A1, HSD3B1, HSD3B2, CYP17A1, CYP21A1, and CYP11B1 and not expressing CYP11B2." (PMID 32680985, 2020).
acne (1 paper, 2021). An inflammatory process of the sebaceous glands which is characterized by comedones, nodules, papules and/or pustules on the skin. "A Chinese study found that HSD3B1 (Hydroxy-Delta-5-Steroid Dehydrogenase, 3 Beta- and Steroid Delta-Isomerase 1) rs6428829 and AAT haplotype, and HSD17B3 (Hydroxysteroid 17-Beta Dehydrogenase 3) H8 haplotype were significantly associated with acne risk." (PMID 33849530, 2021).
adenoma (1 paper, 2022). A neoplasm arising from the epithelium.
adrenal hyperplasia (1 paper, 2014). "has shown that adrenal hyperplasia observed in IHA patients was immunoreactive for type I 3β-hydroxysteroid dehydrogenase (HSD3B1), whereas APA was immunoreactive for type II 3β-hydroxysteroid dehydrogenase (HSD3B2), not for HSD3B1." (PMID 25239966, 2014).
adrenal tumors (1 paper, 2022). "The HSD3B1 gene encodes a rate-limiting enzyme required for all pathways of dihydrotestosterone synthesis and is abundantly expressed in adrenal tumors." (PMID 35563252, 2022).
atopic dermatitis (1 paper, 2024). "In atopic dermatitis, genes mainly related to lipid metabolism (e.g. ACAD8, FADS6, or EBP) as well as disease-specific genes, i.e., Th2 inflammation-related lipid-regulating HSD3B1 were differentially expressed." (PMID 38433843, 2024).
bone tumors (1 paper, 2019). "Enzalutamide treatment resulting in suppression of AKR1C3 and HSD3B1/2 in tumor cells leads to inhibition of bone tumor growth." (PMID 31638934, 2019). "Western blotting analyzed VCaP bone tumor samples for ERG, AR, AKR1C3 and HSD3B1 and HSD3B2 expression." (PMID 31638934, 2019). "Bone tumor analysis shows that ERG knockdown results in diminished expression of AKR1C3 and HSD3B1 in bone tumors." (PMID 31638934, 2019). "To determine enzalutamide responsiveness is related to androgen synthesis in bone tumors, we evaluated the expression of key enzymes in androgen synthesis, AKR1C3, HSD3B1 and HSD3B2, in bone tumors." (PMID 31638934, 2019).
Colon Cancer (1 paper, 2022). "In this study, we demonstrated that IL4 greatly increased the HSD3B1 expression at both the mRNA and protein levels in the HT-29 colon cancer cells." (PMID 36362361, 2022). "Here, we demonstrated that administration of IL4 to an HT-29 colon cancer cell line induced high expression of HSD3B1 at the mRNA and protein levels." (PMID 36362361, 2022). "As HSD3B1 is essential for steroid hormone biosynthesis, our results suggest that IL4 may play a crucial role in the regulation of active steroid synthesis in colon cancer cells." (PMID 36362361, 2022). "IL4 stimulates 3β-HSD activity in colon cancer cell line HT-29; however, the regulation of IL4-mediated HSD3B1 expression is not yet understood." (PMID 36362361, 2022).
diabetes (1 paper, 2021). "The application of Likelihood-ratio tests and Wald statistical tests permitted to define that HSD3B1 polymorphism subgroups status was significantly associated with diabetes concerning ICU admission." (PMID 35874037, 2021). "In addition, in the group of patients with a HSD3B1 heterozygous profile (P1245A>C), the probability corresponded to 20% for patients with diabetes and 15.60% for patients without diabetes." (PMID 35874037, 2021).
heart failure (1 paper, 2016). Inability of the heart to pump blood at an adequate rate to meet tissue metabolic requirements. "Looking for known genes under the linkage peaks, we found two variants previously related to heart failure, TTN (rs72648923; P = 5.5 × 10-2, MAF = 1.4 × 10-2) and HSD3B1 (P = 3.9 × 10-2 MAF = 1.1 × 10-2)." (PMID 27877193, 2016). "Rare variant analysis in these regions uncovered two genes related to heart failure, TTN (P = 5.5 × 10-2) and HSD3B1 (P = 3.9 × 10-2) and one gene with unknown cardiac function FCRL2 (P = 2.8 × 10-4)." (PMID 27877193, 2016).